CDA (cytidine deaminase)
Diseases named in the same sentence as CDA in open-access papers (continued):
Sharing a sentence is not in itself a finding about the gene and the disease.
leukemia (12 papers, 2012 to 2026). A malignant (clonal) hematologic disorder, involving hematopoietic stem cells and characterized by the presence of primitive or atypical myeloid or lymphoid cells in the bone marrow and the blood. "CDA treatment can cause the death of Jurkat human T leukemia cells by inducing apoptosis in a time- and dose-dependent fashion." (PMID 30002603, 2018). "The silence of CDA in leukemia would inhibit tumor growth and promote cell apoptosis in Chronic Myeloid Leukemia (CML) cells." (PMID 34930261, 2021). "CDA is a widely used chemotherapeutic agent in the treatment of certain leukemia and has high expression in cancer cells, which is regarded as a prominent enzyme in the catabolism of cytosine nucleoside analogues." (PMID 30002603, 2018). "CDA treatment has been reported to increase the phosphorylation of ERK1/2 in Jurkat T leukemia cells." (PMID 30002603, 2018). "Recipient cell methyltransferase and cytidine deaminase can be downregulated by onco-mRNA in microvesicles derived from leukemia cells." (PMID 26582468, 2015). "Recently, CDA-2 was found to inhibit activation of NF-κB in human leukemia and myelodysplastic syndromes (MDS) cell lines in vitro through an impact on NF-κB nuclear translocation by affecting IkBα phosphorylation and degradation." (PMID 23284890, 2012). "Interestingly, patients with higher pretreatment leucocyte or blast counts have a faster clearance because of the cytidine deaminase activity in leukemia cells." (PMID 41010660, 2025). "For this reason, we speculated that CDA could become a promising biomarker and therapeutic target for the treatment of leukemia." (PMID 30002603, 2018). "Among leukemia-derived cell lines, MDS-L, an MDS-derived cell line with a relatively low CDA expression level, was found to be the most sensitive to 5AC." (PMID 31040918, 2019). "Therefore, CDA gene silencing may become an effective target for the treatment of leukemia." (PMID 30002603, 2018). "To detect the transcription of DCK, CDA and SLC29A1, we examined mRNA expression of these genes in the leukemia blasts from the bone marrow of AML patients." (PMID 25398670, 2014). "The levels of CDA expression and activity in ATL cells and other leukemia and lymphoma cells are unknown." (PMID 33167425, 2020).
lung carcinoma (11 papers, 2009 to 2023). "Clinically, CDA expression is associated with the EMT signature in lung cancer patients." (PMID 35999456, 2022). "To exclude that the toxicity of DHODHi+cytidine in cells grown with iFBS is only characteristic of neuroblastoma cells we compared its effects on lung cancer cell lines as these include low as well high CDA-expressing cells." (PMID 36424385, 2022). "To explore the clinical relevance of CDA in lung cancer, we analyzed CDA expression in lung adenocarcinomas using GEPIA35, a tool for analyzing the Cancer Genome Atlas (TCGA) and Genotype-Tissue Expression (GTEx) databases." (PMID 35999456, 2022). "In summary, treatment with chemotherapy results in increased CDA/TYMP expression during the recovery phase thereby sensitizing lung cancer cells to subsequent 5′-DFCR treatment." (PMID 33874986, 2021). "We found that treatment with chemotherapy results in increased CDA/TYMP expression during the recovery phase thereby sensitizing lung cancer cells to subsequent 5′-DFCR treatment." (PMID 33874986, 2021). "5′-DFCR was found to selectively inhibit the growth of chemotherapy-resistant lung cancer cells featuring increased CDA and TYMP expression." (PMID 33874986, 2021). "Chemotherapy increases CDA and TYMP expression thereby rendering resistant lung cancer cells susceptible to subsequent 5′-DFCR treatment." (PMID 33874986, 2021). "We identified RAC2 and CDA as genes with significantly higher expression in PD-L1-high lung cancer cell lines." (PMID 27846317, 2016). "This is consistent with lung cancer analyses, where subclonal lineages acquired mutations that lacked the tobacco-smoking signature and were replaced with mutations associated with APOBEC cytidine deaminase activity." (PMID 32855398, 2020). "Thus, CDA appears to have a key role in EMT during lung cancer progression." (PMID 35999456, 2022). "CDA + 435, and SLC28A1 + 1561 are worthy of further investigation as potential indicators of patient outcome after gemcitabine treatment in lung cancer." (PMID 37150853, 2023). "Further, the increase of CDA and TYMP expression after treatment with chemotherapy was more pronounced in KRAS mutant lung cancer cells." (PMID 33874986, 2021). "Thus, our study reveals that the chemotherapy-induced increase in pyrimidine salvage pathway expression, e.g., increased CDA and TYMP, might be exploited in the clinical setting to target therapy-resistant lung cancer by schedule-dependent treatment with Capecitabine." (PMID 33874986, 2021). "BICD2, CDA, NMNAT2, SERPINB13, and TOX3 have no specificity to either AC or SCC but to lung cancer." (PMID 19761563, 2009).
pancreatic ductal adenocarcinoma (10 papers, 2018 to 2025). An infiltrating adenocarcinoma that arises from the epithelial cells of the pancreas. "Pancreatic ductal adenocarcinoma programmed TAMs not only facilitated their own uptake of gemcitabine by upregulating CDA expression, but also competitively inhibited the uptake of gemcitabine by tumor cells through deoxycytidine secretion 73,74." (PMID 40084259, 2025). "Gemcitabine, a pyrimidine nucleoside, is detoxified in pancreatic ductal adenocarcinoma due to the activity of the long isoform of the enzyme cytidine deaminase expressed by intratumoral Mycoplasma hyorhinis." (PMID 40761254, 2025). "The study highlighted major differences in CDA plasma activity when cases of metastatic versus resectable pancreatic ductal adenocarcinoma were compared." (PMID 37208732, 2023). "High expression of cytidine deaminase in chemo-resistant, metastatic pancreatic ductal adenocarcinoma, and chemoresistant lymphoid malignancies is one reason for decitabine treatment failure." (PMID 34880864, 2021). "Activated platelets release ADP and ATP, which activated ADP purinergic receptor P2Y12 expressed on pancreatic ductal adenocarcinoma and hence promoted expression of gemcitabine resistance markers Slug and cytidine deaminase (CDD)." (PMID 34322664, 2021). "A recent study found that CDA localises to replication forks and that CDA overexpression in pancreatic ductal adenocarcinoma models improves replication dynamics, suggesting that it could be part of a machinery aimed at locally increasing the provision of nucleotides during DNA replication." (PMID 39206868, 2024). "Activated platelets in tumor cells release ADP in the extracellular compartment, and ADP-activated P2Y12 in pancreatic ductal adenocarcinoma (PDAC) increased expression of markers for gemcitabine resistance like human equilibrative nucleoside transporter 1 (hENT1) and cytidine deaminase (CDD)." (PMID 36741002, 2023).
viral infection (9 papers, 2005 to 2023). "In general, cytidine deaminase is involved in biological diversity, such as reprograming toward pluripotency, immunoglobulin diversification, immune responses to viral infection and cancer mutagenesis." (PMID 28498833, 2017). "SAMHD1 is a deoxynucleoside triphosphohydrolase that interferes with viral infection mostly by limiting the intracellular concentrations of dNTPs, while A3A is a cytidine deaminase that has been described to edit incoming vDNA." (PMID 26496699, 2015). "A3G largely functions as a CDA during reverse transcription after packaging into virions, while A3A seems to work in target cells to block incoming virus infection, either via deaminase-dependent or –independent means." (PMID 24851906, 2014). "The cytidine deaminase cargo results in hypermutation of the replicating virus in target cells, thereby inhibiting virus infection." (PMID 15998449, 2005). "Another proposed mechanism is the direct viral infection of B lymphocytes: HCV-infected cells, including B cells, have been found to have a mutator phenotype due to the induction of activation-induced cytidine deaminase and the production of error-prone DNA polymerase." (PMID 36975729, 2023). "However, whereas the cytidine deaminase inhibits virus infection at the reverse transcription step, adenosine deaminase may affect the HIV-1replication at a post-transcription stage." (PMID 25272020, 2014). "C60 nanofilm also downregulated cytidine deaminase apolipoprotein (APOBEC3A, or A3A), whose main function is the deamination of cytosine to uracil during mutagenesis and viral infections." (PMID 38067256, 2023). "In addition, at a post-transcriptional level, members of the human cytidine deaminase APOBEC3 family, involved in the response against viral infection, inhibit the activity of L1 retrotransposons." (PMID 28049704, 2017).
colon cancer (8 papers, 2018 to 2024). "As shown in Fig. 8A1, gene knockdown of CDA resulted in marked inhibition of DNMT1 protein following decitabine treatment of colon cancer cells, and the results of 3 independent experiments are given as histograms (Fig. 8A1)." (PMID 37208732, 2023). "Similarly, there is precedent to treat gastrointestinal problems with E. siraeum, and activation-induced cytidine deaminase seems to prevent colon cancer development despite persistent inflammation in the colon." (PMID 39240096, 2024). "Therefore, we performed gene knockdown studies to repress CDA transcript expression in decitabine-treated colon cancer cells." (PMID 37208732, 2023). "Our study provides a molecular rationale for first-line treatment of colon cancer patients with a combination of DNMT, CDA and histone deacetylase inhibitors." (PMID 37208732, 2023). "Data from mouse models of colon cancer suggest that resistance to Gemcitabine may be the result of increased metabolic degradation of Gemcitabine into difluorodeoxyuridine by the long isoform of the bacterial enzyme cytidine deaminase (CDDL), mainly found in the γ-amastigotes phylum." (PMID 36212852, 2022). "Although decitabine treatment of colon cancer cells repressed DNMT1 protein expression by about 30% (Fig. 8A1), the additional gene knockdown of CDA enhanced decitabine’s ability to promote DNMT1 protein degradation, and depending on the cell line, its expression was reduced between 80 and 90%." (PMID 37208732, 2023).
acute myeloid leukemia (7 papers, 2015 to 2025). Acute myeloid leukemia (AML) is a group of neoplasms arising from precursor cells committed to the myeloid cell-line differentiation. "Some current studies have also shown that CDA has high efficacy in treating acute myeloid leukemia, mainly through the PI3K/Akt pathway, which regulates apoptosis and thus influences the disease’s pathological process." (PMID 40861421, 2025). "However, it does contain expression data for other tumor types where the expression of CDA mRNA is not consistently low (e.g., melanoma, non-small cell lung carcinoma, and acute myeloid leukemia) for comparison with the expression of CDA in retinoblastoma samples." (PMID 38332874, 2024). "Further study demonstrated that the prognosis of acute myeloid leukemia (AML) with the treatment of Cytarabine was strongly related to the expression of CDA." (PMID 34930261, 2021). "Acute myeloid leukemias are not amongst the cancer types that consistently show low CDA levels, except perhaps for childhood AML according to the available data." (PMID 36424385, 2022).
colorectal cancer (7 papers, 2015 to 2025). A primary or metastatic malignant neoplasm that affects the colon or rectum. "With regards to cancer, A3G has been shown to promote liver metastasis in an orthotopic mouse model of colorectal cancer, sensitize mesenchymal gliomas to radiation-induced cell death, and enhance lymphoma cell radio resistance by promoting cytidine deaminase-dependent DNA repair." (PMID 34625538, 2021). "The authors then investigated if overexpressing CDA in the anti-PD-1-responsive colorectal cancer model, MC38, could induce ICI resistance and found that these cells now displayed elevated aggression and resistance to anti-PD-1 therapy due to poor T cell response induction." (PMID 40011298, 2025). "Overall, CDA induction in cancer cells mediates anti-PD-1 resistance in different tumor types, such as PDAC, melanoma and colorectal cancer." (PMID 38844817, 2024). "For example, HCT116 colorectal cancer cells, resistant to prolonged DAC treatment, showed increased mRNA expression of secreted frizzed related protein 1 and protein expression of cytidine deaminase, while that of deoxycytidine kinase was decreased." (PMID 32194414, 2020). "Thus, increased CDA activity leads to anti-PD-1 resistance in PDAC, melanoma and colorectal cancer cells." (PMID 40011298, 2025).
lymphoma (7 papers, 2019 to 2024). A malignant (clonal) proliferation of B- lymphocytes or T- lymphocytes which involves the lymph nodes, bone marrow and/or extranodal sites. "A3G, a member of the APOBEC3 family, is a CDA that is predominantly expressed in lymphoma cells and is involved in mutational double-strand DNA break repair; therefore, APOBEC-dependent mutational processes should be investigated." (PMID 33167425, 2020). "The findings revealed that BCL2 mutations are linked to increased activation-induced cytidine deaminase production, altered antiapoptotic BCL2 function, and a higher probability of lymphoma transformation and death." (PMID 36831357, 2023). "Here, we show that the related cytidine deaminase, APOBEC3G, induces site-specific C-to-U RNA editing in natural killer cells, lymphoma cell lines, and, to a lesser extent, CD8-positive T cells upon cellular crowding and hypoxia." (PMID 30791937, 2019).
melanoma (7 papers, 2013 to 2025). A malignant, usually aggressive tumor composed of atypical, neoplastic melanocytes. "This low dose 5-AZA-CdR, in combination with tetrahydrouridine to inhibit cytidine deaminase, was also very effective in inhibiting the growth of murine melanoma tumors in mice." (PMID 23369223, 2013). "However, treatment with 5-Aza-2′-Deoxycytidine (5-Aza-dC), a DNA methyltransferase activity inhibitor, significantly increases CDA expression in cancer cell lines derived from breast, lung ovarian and melanoma tumors with a low initial CDA expression level." (PMID 33874986, 2021). "When CDA inhibition was coupled with anti-PD-1 treatment, the anti-PD-1 resistant orthotopic YUMM1.7 melanoma cell line had decreased tumor growth and increased CD8+ T cell activation." (PMID 40011298, 2025).
non-small cell lung carcinoma (7 papers, 2009 to 2024). A group of at least three distinct histological types of lung cancer, including non-small cell squamous cell carcinoma, adenocarcinoma, and large cell carcinoma. "Deficiency of MSC after silencing cytidine deaminase may trigger anti-proliferative effects on ceritinib-resistant non-small-cell lung cancer." (PMID 38466483, 2024). "Non-small cell lung carcinoma (NSCLC) cell lines showed a significantly high expression of CDA in comparison to the other malignancies (two-sided Welch’s T-test, FDR = 3.18 × 10−11)." (PMID 36424385, 2022). "The aim of this prospective study was to validate the prognostic role of CDA activity in the first-line treatment of advanced non-small-cell lung cancer." (PMID 30405211, 2018).
Bloom syndrome (6 papers, 2015 to 2023). Bloom syndrome (BSyn) is a rare chromosomal breakage syndrome characterized by a marked genetic instability associated with pre- and postnatal growth retardation, facial sun-sensitive telangiectatic erythema, increased susceptibility to infections, and predisposition to cancer. "We also show that CDA deficiency makes a major contribution to several aspects of the cellular phenotype associated with Bloom syndrome." (PMID 26181065, 2015). "A deficiency of cytidine deaminase (CDA) might result in replication stress, and might lead to Bloom syndrome." (PMID 37240761, 2023). "Cells from Bloom’s syndrome patients display genome instability due to a defective BLM and the downregulation of cytidine deaminase." (PMID 28947735, 2017).
myelodysplastic syndrome (6 papers, 2012 to 2024). A clonal hematopoietic disorder characterized by dysplasia and ineffective hematopoiesis in one or more of the hematopoietic cell lines. "Recently, the FDA approved ASTX727, an oral formulation of a fixed-dose combination of DAC and cedazuridin (a cytidine deaminase inhibitor), for the treatment of adult patients with myelodysplastic syndromes and chronic myelomonocytic leukemia." (PMID 37894456, 2023).
bladder cancer (4 papers, 2013 to 2025). "Transfection of human CDA into gastric cancer cell lines reduced their sensitivity to GEM both in vitro and in vivo and forced expression of CDA increased the sensitivity of bladder cancer cells to DFCR but made them resistant to GEM in vitro and in vivo." (PMID 23840665, 2013). "The result showed that TERT was not expressed in normal bladder but overexpressed in bladder cancer with core promoter C228T mutation TERT; survival data of CDA, SLC9A1 and SLC24A4 also showed that their expression levels were associated with 5-year survival significantly." (PMID 35033028, 2022).
cervical cancer (4 papers, 2012 to 2022). A primary or metastatic malignant neoplasm involving the cervix. "However, the high expression of CXCL8, TNFAIP6, CXCL5 and CDA in cervical cancer tissues was associated with a poor patient prognosis." (PMID 34174849, 2021). "Pathway analyses revealed that the most significantly mutated gene set in cervical cancer involved a deficiency of DNA mismatch repair, APOBEC-cytidine deaminase, and spontaneous deamination of 5-methyl cytosine." (PMID 33664766, 2021). "Moreover, APOBEC cytidine deaminase mutagenesis pattern has been detected in human cervical cancer." (PMID 33664766, 2021). "Cervical cancer cell lines were examined for the basal expression of hENT1, dCK, RRM1, RRM2, CDA genes and then their sensitivity to gemcitabine was evaluated." (PMID 22427797, 2012).
gastric cancer (4 papers, 2013 to 2026). A primary or metastatic malignant neoplasm involving the stomach. "Infection with Helicobacter pylori can directly induce DNA double-strand breaks in gastric epithelial cells and enhance the activity of cytidine deaminase (CDA) enzymatic activity, leading to genetic damage and promoting gastric cancer through dysplasia." (PMID 41602751, 2026).